RN7SKP258 (RN7SK pseudogene 258)
Gene: Miscellaneous RNA gene on chromosome 9 (18,651,147 to 18,651,450, forward strand). Ensembl gene ENSG00000252960.
Homologues: Orthologues: chimpanzee 7SK (98% identical), mouse Gm54834 (41% identical), guinea pig 7SK (37% identical), mouse Gm55071 (17% identical). Paralogues in human: RN7SKP180 (57% identical), RN7SKP178 (57% identical), RN7SKP269 (57% identical), RN7SKP78 (57% identical), 7SK (56% identical), RN7SKP1 (56% identical), RN7SKP131 (56% identical), RN7SKP48 (56% identical), RN7SKP63 (56% identical), RN7SKP133 (56% identical), RN7SKP200 (56% identical), RN7SKP221 (56% identical), and 284 more.